BDNF (brain derived neurotrophic factor)
Diseases named in the same sentence as BDNF in open-access papers (continued):
Sharing a sentence is not in itself a finding about the gene and the disease.
Parkinson disease (continued). "Recent findings on changes in expression levels of neurotrophic factors in hα-Syn transgenic mice suggest that altered BDNF levels could be linked to onset and progression of Parkinson’s disease." (PMID 23302418, 2013). "Furthermore, interactions between cathepsins and other biomarkers, as well as genetic variabilities such as apolipoprotein E and Brain-Derived Neurotrophic Factor (BDNF), may contribute to the risk of Parkinson’s disease." (PMID 38903897, 2024). "A meta-analysis reported that serum BDNF decrease in individuals affected by Parkinson Disease (PD), supporting the association of reduced BDNF level and PD." (PMID 35668928, 2022). "Finally, training-evoked increase of the BDNF/TrkB leads to a change in a manner of regulation of skeletal muscles, causes a reduction of motor deficits observed in the Parkinson disease, and lowers weight, glucose level, and blood pressure, which accompany the MetS." (PMID 31341469, 2019). "A loss of GABAergic (Gamma-Aminobutyric Acid) neurons in the substantia nigra contributes to Parkinson’s pathology, and BDNF protects them from excitotoxicity." (PMID 41199384, 2025). "Several studies reported that BDNF support proper striatum functions and the BDNF/TrkB pathway is important in motor coordination including in pathological context such as parkinsonism." (PMID 40717895, 2025). "BDNF, being the most studied, enhances neuronal survival, differentiation, and long-term potentiation—key in Alzheimer’s disease (AD), Parkinson’s disease (PD), Huntington’s disease (HD), MS, traumatic brain injury (TBI), and spinal cord injury (SCI)." (PMID 40943142, 2025). "Activation of the PI3K/AKT and BDNF/CREB signaling pathways has been recognized as a key factor in reducing neuronal apoptosis in mouse models of Parkinson’s disease." (PMID 40650274, 2025). "For example, STAT3 phosphorylation and neuronal autophagy are promoted by brain-derived neurotrophic factor (BDNF), a promising agent for targeting Parkinson’s disease." (PMID 39508990, 2025). "In Parkinson’s disease, BDNF maintains dopaminergic neuron function in the substantia nigra pars compacta." (PMID 41199384, 2025). "The therapeutic potential of BDNF mimetics in Alzheimer’s (AD), Parkinson’s Disease (PD), and Huntington’s disease (HD) remains in the preclinical stage." (PMID 40362877, 2025). "Exosomes stimulate the regeneration of dopaminergic neurons and improve motor function recovery in Parkinson’s disease animals by delivering BDNF directly to the damaged regions." (PMID 40095345, 2025). "To further explore the cognitive improvement and neuroprotective effects of aerobic exercise in Parkinson’s disease mice, we examined the expression of brain-derived neurotrophic factor (BDNF) using western blotting." (PMID 41195080, 2025). "The relative content of BDNF in the hippocampus of mice in the aerobic exercise group (BDNF/Internal Reference Protein) was significantly higher than that in Parkinson’s disease mice." (PMID 41195080, 2025). "BDNF is increasingly preferred over GDNF in various Parkinson’s disease therapy models due to its broader neuroprotective profile and practical advantages in delivery." (PMID 41199384, 2025). "Brain-Derived Neurotrophic Factor exerts its effects in Parkinson’s disease at the cellular level via high-affinity binding to its receptor, TrkB." (PMID 41199384, 2025). "While BDNF has neuroprotective effects in conditions like Alzheimer's and Parkinson's disease, its role in airway diseases is multifaceted and context-dependent." (PMID 40034284, 2025). "BDNF has shown therapeutic potential in Parkinson’s Disease, but is limited by its short half-life and inability to penetrate the Blood–Brain Barrier (BBB)." (PMID 41199384, 2025). "BDNF has been linked to improved cognition, learning, memory formation, and modulation of synaptic plasticity in animal models, and a decrease in BDNF levels is observed in NDs such as Parkinson's." (PMID 40904189, 2025).
Parkinson disease (continued). "The combination of stem cell therapy and BDNF enhancement represents a promising and innovative direction in Parkinson’s disease treatment." (PMID 41199384, 2025). "Potential primary outcomes for a full trial were serum brain‐derived neurotrophic factor, maximal oxygen uptake and the Unified Parkinson's Disease Rating Scale part III." (PMID 40661734, 2025). "Longitudinal studies have demonstrated that patients with serum BDNF levels < 10 ng/mL have a 30% increased rate of annual decline in motor function (up to 30% as measured on the Unified Parkinson’s Disease Rating Scale scores)." (PMID 40362507, 2025). "For instance, exosomes containing brain-derived neurotrophic factor (BDNF) generated from human umbilical cord mesenchymal stem cells (MSC) have demonstrated potential in models of Parkinson’s disease." (PMID 40095345, 2025). "The BDNF/GDNF pathway was commonly regulated by exercise training in the nigrostriatum of various Parkinson’s models, providing neurotrophic support by upregulating BDNF and GDNF proteins and downregulating MAPK and p-Erk1/2, thus facilitating CREB activation." (PMID 39844853, 2024). "Increased levels of BDNF not only have beneficial effects in healthy older adults but also play an important role in Parkinson’s patients." (PMID 39456138, 2024). "Supporting this notion, BDNF is posited to act as a crucial mediator linking physical activity with the alleviation of neurodegenerative diseases such as Alzheimer’s and Parkinson’s disease." (PMID 39935805, 2024). "The authors also discussed potential strategies to elevate BDNF levels in the brain as a therapeutic approach for managing Parkinson’s disease." (PMID 39935805, 2024). "Reduced serum levels of BDNF have been observed in various neurological conditions, including neurodegenerative diseases such as AD, Huntington's disease (HD), and Parkinson's disease (PD), as well as mood disorders like depression and bipolar disorder." (PMID 39648181, 2024). "Other small molecules, such as drugs (ampakines, memantine, and riluzole), significantly enhance the expression and release of BDNF to treat Alzheimer’s and Parkinson’s diseases." (PMID 39239097, 2024). "This review brings together evidence on the role of BDNF in motor control and neuroprotection that essentially contribute to the pathophysiology of Parkinson’s disease and possibly dystonia." (PMID 39200225, 2024). "For example, exercise therapy has proven to be effective in raising BDNF levels in the blood and attenuating motor symptoms in patients with Parkinson’s disease." (PMID 39200225, 2024). "For example, several studies showed that individuals with Parkinson's disease had significantly lower serum levels of BDNF." (PMID 39712854, 2024). "BDNF levels in neurodegenerative diseases such as multiple sclerosis (MS), Parkinson’s, and Huntington’s disease." (PMID 39810851, 2024). "A decline in BDNF levels within the plasma and cortex is followed by a rise of dopaminergic neuronal degradation in Parkinson’s disease, resulting in behavioral abnormalities, intellectual deficiencies, and psychiatric illness, which impairs memory." (PMID 37287291, 2024). "BDNF is dysregulated in different neurodegenerative diseases such as Alzheimer's disease (AD) and Parkinson's disease (PD)." (PMID 39654365, 2024). "BDNF is a potential drug for treating Parkinson’s disease since it has been shown to have neuroprotective and neurorestorative effects on dopaminergic neurons." (PMID 37780709, 2023). "Previous studies have shown reduced BDNF mRNA and protein expression in different brain regions of AD patients and in the substantia nigra of subjects diagnosed with Parkinson’s disease." (PMID 36830773, 2023). "In experimental models of Parkinson’s disease, a therapeutic effect has been achieved with BDNF overexpression or with BDNF administration." (PMID 37239153, 2023).
Parkinson disease (continued). "Non-pharmacological strategies such as exercise can improve learning and memory impairment by upregulating the BDNF pathway in animal models of AD and in Parkinson’s disease." (PMID 36720792, 2023). "A study demonstrated that BDNF was loaded into macrophage-derived exosomes and applied for Parkinson’s disease therapy." (PMID 35327480, 2022). "Abundant data have suggested a role for impaired BDNF/TrkB signaling in the etiology of Parkinson’s disease, at least from in vivo animal models." (PMID 35321093, 2022). "Several clinical trials performed on Parkinson’s disease involved use of implanted devices to infuse BDNF, with high flow rates needed to achieve the desired concentration in the putamen." (PMID 35625880, 2022). "BDNF has demonstrated great promise in treating animal models of several diseases including ischemic stroke, Alzheimer’s disease, Parkinson’s disease, etc.." (PMID 35890287, 2022). "Accordingly, augmenting BDNF is a promising therapeutic strategy in Parkinson’s disease, not only by protecting from dopaminergic neuronal degeneration but also via augmenting dopaminergic transmission, as supported by preclinical and clinical evidence." (PMID 35955546, 2022). "Specifically in people with Parkinson's disease, which represents the majority (85%) of participants in the present study, BDNF and exercise have been shown to stimulate growth and survival of dopaminergic neurons in the substantia nigra pars compacta." (PMID 36742042, 2022). "Previously, we showed that dioscin is a potential neuroprotector in an MPP+-induced Parkinson’s disease model, where dioscin showed a substantial reduction of apoptosis and upregulated neurotrophic factors such as BDNF and pCREB." (PMID 36077321, 2022). "This reduction was profound, prompting us to examine BDNF expression in buffy coat samples from patients with parkinsonism (n = 5)." (PMID 35008438, 2021). "In this study, the protective effect of quercetin was investigated on memory and cognition, antioxidant defense‎, and hippocampal BDNF concentration in the 6-OHDA-induced Parkinson's rat model." (PMID 34804897, 2021). "Treadmill training appeared to enhance BDNF and complex I level to reduce the progressive development of Parkinson’s disease." (PMID 34440215, 2021). "Several studies have shown that estrogen depletion leads to decreased BDNF protein expression in the hippocampus and cortex regions in Alzheimer’s and Parkinson’s diseases." (PMID 33953866, 2021). "The neuroprotective effects of metformin were also seen in mouse models of Parkinson’s disease with increased BDNF protein levels observed in metformin-treated mice." (PMID 34439919, 2021). "Brain content of the neurotrophin BDNF is decreased in AD, Huntington disease and Parkinson's disease." (PMID 34276338, 2021). "We assessed the effect of quercetin administration on memory and motor function, hippocampal ‎ oxidative stress and brain-derived neurotrophic factor (BDNF) level in a 6-OHDA-induced Parkinson's rat model." (PMID 34804897, 2021). "Thereby, glial cell line-derived neurotrophic factor (GDNF), brain-derived neurotrophic factor (BDNF) and nuclear factor E2-related factor 2 (Nrf2) have been studied for Parkinson’s disease treatment." (PMID 33233374, 2020). "Previous studies showed that PKA provided important neuroprotective effects and reduced neuronal apoptosis through the p38 MAPK/CREB or CREB/BDNF signaling pathway in various CNS conditions, including ischemic brain injury, Parkinson's disease, and AD." (PMID 33101590, 2020). "The reduced expression of BDNF in nigral neurons in patients with Parkinson's disease and in rats with lesions of the nigro-striatal innervation also suggests its participation in the pathogenesis of the disease." (PMID 33269104, 2020).
Parkinson disease (continued). "A combination of rasagiline and EGCG was found to restore C57/BL6 mice from MPTP induced parkinsonism by increasing the dopamine level, inducing the expression of BDNF, phosphorylated PKC-α as well as Ras and its downstream effector Akt." (PMID 32867388, 2020). "In the vast majority of studies with BDNF administration before induction of parkinsonism, the research results revealed at least partial prevention of neuronal cell loss." (PMID 32050617, 2020). "Expression of the BDNF gene is reduced in patients with several neurodegenerative diseases, including Alzheimer’s, Parkinson’s, and Huntington’s disease." (PMID 32291635, 2020). "Changes in the concentration and activity of neurotrophins, especially BDNF, are also of key importance in the pathogenesis of neurodegenerative diseases (AD, Parkinson’s disease (PD), Huntington’s disease, dementia) and neurodevelopmental disorders (ASD)." (PMID 31443560, 2019). "CR also improved behavioral and molecular signs in a MPTP-induced mouse model of Parkinson’s Disease (PD) by increasing the levels of the brain derived neurotrophic factor and the glial cell-derived neurotrophic factor." (PMID 31905682, 2019). "An increase of BDNF in response to physical training was recorded in healthy subjects as well as among Parkinson’s disease patients." (PMID 30241318, 2018). "Postmortem brain studies have suggested that BDNF is involved in the pathogenesis of Parkinson’s disease (PD)." (PMID 29867348, 2018). "Regarding the relationship between BDNF and motor functioning, many articles focus on Parkinson's disease, where limited MF appears to indicate lower levels of peripheral BDNF." (PMID 29896133, 2018). "Experimental studies of Parkinson's disease in animals have also shown an upregulation in BDNF in response to aerobic exercise with related improvement in symmetrical forelimb movement and improved balance." (PMID 29057125, 2017). "In the 6-hydroxydopamine-induced Parkinson’s disease rat model, administration of SB resulted in a substantial attenuation of motor deficits and also in an increase of striatal dopamine, BDNF, and global H3 histone acetylation levels." (PMID 29246185, 2017). "On this basis, we propose that BDNF overexpression in surviving DA neurons in the early stage of Parkinsonism will prevent the nigrostriatal deterioration." (PMID 26198255, 2015). "This study aimed to demonstrate that increasing BDNF expression in dopaminergic neurons of rats with one week of 6-hydroxydopamine lesion recovers from parkinsonism." (PMID 26198255, 2015). "The expressed BDNF-flag produced partial biochemical, structural, and behavioral recovery from early parkinsonism." (PMID 26198255, 2015). "Specifically, glial cell-derived neurotrophic factor (GDNF), nerve growth factor (NGF), and brain derived neurotrophic factor (BDNF) have been recognized as therapeutic trophic factors for Parkinson’s, Alzheimer’s and Huntington’s diseases, respectively." (PMID 24463293, 2014). "BDNF has also been described to play a neuroprotective role for dopaminergic neurons that are depleted in the substantia nigra in Parkinson's disease." (PMID 24391835, 2013). "BDNF levels are generally decreased in the brain of patients suffering from Alzheimer’s, Parkinson’s or Huntington’s diseases." (PMID 24300402, 2013). "In brain tissue of Parkinson's disease patients, GDNF, NGF, and brain-derived neurotrophic factor (BDNF) are deficient, hence the clinical trials of therapeutic GDNF injection into the brain of Parkinson's patients." (PMID 24023412, 2013). "Both protein and mRNA levels of BDNF are decreased in dopaminergic neurons of the substantia nigra, the neurons most vulnerable in Parkinson’s disease." (PMID 23210531, 2012). "Mice fed a DHA-rich diet had significantly higher levels of brain-derived neurotrophic factor (BDNF) in the striatum, an area of the brain involved in Parkinson’s Disease." (PMID 22254110, 2011).
Parkinson disease (continued). "Alterations in BDNF expression can contribute to serious pathologies such as epilepsy, Huntington, Alzheimer's, and Parkinson's disease." (PMID 19737418, 2009). "Of note, GDNF is more effective than BDNF in protecting nigrostriatal neurons in the 6-OHDA rat model of Parkinson's disease." (PMID 18402684, 2008). "Similarly, BDNF gene therapy has been investigated for various neurodegenerative diseases, including Parkinson's, Alzheimer's, and Huntington's diseases." (PMID 41480410, 2026). "Additionally, FUSIN delivery of brain-derived neurotrophic factor (BDNF) was reported to produce neurorestorative effects in a Parkinson's disease mouse model." (PMID 41424850, 2026). "This is the first research in which FSH priming during CEPs of the NS assay is combined with directed differentiation of NSPCs towards the DA pathway by using a defined medium containing SHH, FGF8, and BDNF, a procedure with possible eventual clinical implications for Parkinson’s disease therapy." (PMID 40722636, 2025). "Consequently, while GDNF remains valuable in dopaminergic regeneration, BDNF offers a more feasible and versatile therapeutic option in the current landscape of Parkinson's treatment development." (PMID 41199384, 2025). "BDNF, that is also reduced in Parkinson’s condition, may be useful for preventing the pathological loss and providing neuroprotection." (PMID 41009546, 2025). "Additionally, BDNF is recognized for its neuroprotective effects in response to stress and in neurodegenerative diseases, such as Alzheimer's disease and Parkinson's disease." (PMID 40034284, 2025). "The synthesis of BDNF induced by orexin may have therapeutic implications also in another neurodegenerative condition: Parkinson’s disease (PD)." (PMID 41009546, 2025). "In Alzheimer’s and Parkinson’s diseases, the levels of brain-derived neurotrophic factor (BDNF), synaptophysin (SYN), and nerve growth factor (NGF) are reduced, leading to impaired synaptic plasticity as well as decreased neuronal density and cholinergic neuron survival in the hippocampus." (PMID 41375975, 2025). "Therefore, this review focuses on evaluating the combined use of stem cell therapy and BDNF modulation as an integrated approach for Parkinson’s disease treatment." (PMID 41199384, 2025). "The presence of the Met allele has been linked to altered intracellular trafficking and reduced activity-dependent release of BDNF, which may exacerbate neuronal vulnerability in conditions such as MS and Parkinson’s." (PMID 40003622, 2025). "Furthermore, BDNF changes correlated with improvements in motor performance, measured by the Unified Parkinson’s Disease Rating Scale (UPDRS) part III motor score, as well as ambulatory capacity and balance." (PMID 40595707, 2025). "Furthermore, evidence suggests that BDNF supports the survival of dopaminergic neurons in animal models of Parkinson’s disease." (PMID 39935805, 2024). "While previous studies have linked exercise to the release of BDNF, aspects such as the influence of different types of exercise (aerobic, resistance, strength) on BDNF modulation in diseases like Alzheimer’s and Parkinson’s have not been explored in depth." (PMID 39935805, 2024). "Strong evidence currently exists connecting BDNF to Parkinson's disease." (PMID 39712854, 2024). "Ongoing clinical trials are exploring BDNF-based therapies for Parkinson's disease." (PMID 39568824, 2024). "Preclinical studies with 6-hydroxydopamine (6-OHDA)-induced early parkinsonism have shown that the targeted delivery of genes coding for neurotrophic factors such as human (hGDNF), rat brain-derived neurotrophic factor (rBDNF), or hCDNF can rescue dopaminergic neurons from neurodegeneration." (PMID 38564106, 2024). "Transplantation of BDNF‐modified human umbilical cord mesenchymal stem cell (hUC‐MSC)‐derived dopaminergic‐like neurons improved the apomorphine‐induced rotation behavior of Parkinson's disease (PD) rats." (PMID 37786546, 2023).